TXNRD1 (thioredoxin reductase 1)
Diseases named in the same sentence as TXNRD1 in open-access papers (continued):
Sharing a sentence is not in itself a finding about the gene and the disease.
tumor (121 papers, 2008 to 2026). "Despite these limitations, on balance our data demonstrate several causative relationships between ROS, Tregs, and tumor burden, including a first described causal relationship between TXNRD1 inhibitors like auranofin and Treg expansion." (PMID 41300507, 2025). "Our analysis revealed that Txnrd1 mRNA (the gene encoding for TrxR1) is significantly overexpressed in GBM tumor tissues compared to normal tissue (p < 0.001)." (PMID 39456455, 2024). "As one of the major REDOX regulators, TXNRD1 is associated with tumor aggressiveness and poor prognosis." (PMID 38097352, 2023). "Subsequently, we constructed a risk model based on four LMAGs—LCAT, MED22, MED7, and TXNRD1—which presented noteworthy prognostic values and was closely associated with tumor grade, tumor stage, and T-staging." (PMID 36330335, 2022). "Enhanced TXNRD1 expression was associated with tumor progression and metastasis and conferred chemotherapy resistance." (PMID 36544763, 2022). "These increases in NRF2-regulated enzymes likely compensated for the oxidative burden of TXNRD1-deficient hepatoma cells once tumor formation occurred." (PMID 26569310, 2015). "TXNRD1 associated with aggressive tumor growth and poor survival rate plays an important role in regulation of TXN." (PMID 26325518, 2015). "In the case of TXNRD1, associations were observed with tumor grade and pT stage, hormone receptor status and ERBB2 status." (PMID 20584310, 2010). "Moreover, TXN and GSH in combination exhibit tumor prevention in mice with combined loss of liver-specific TXNRD1 and GR; having high sensitivity towards carcinogen-induced liver malignancy." (PMID 33477494, 2021). "Also, the Txn1/Txnrd1 system has been frequently linked with proliferation of many tumors and tumor cell lines." (PMID 18350150, 2008). "We demonstrate a direct causal relationship between treatment with the TXNRD1 inhibitors auranofin and TRi-1 and enhanced in vivo B16F10 tumor progression using the syngeneic lung colonization model." (PMID 41300507, 2025). "TXNIP, as well as TXN and TXNRD1 have been demonstrated in several studies to regulate tumor immunity, especially T-cell function and differentiation." (PMID 39744566, 2025). "We found that there was a significant increase in F4/80 staining in TXNRD1 KO tumors compared to all other genotypes, with as much as 40 % of the tumor content being macrophages." (PMID 40334547, 2025). "Auranofin-mediated TXNRD1 inhibition has shown anti-tumor efficacy in multiple cancer models both in vitro and in vivo." (PMID 41300507, 2025). "To gain further insight into the pathophysiological response to TXNRD1 inhibitor treatment in the tumor, we analyzed B16F10 lung foci and analyzed them for differences in protein expression." (PMID 41300507, 2025). "Overall, these findings indicate that although TXNRD1 is dispensable for tumor initiation, TXNRD1 mediates the early tumor progression effects of Nrf2D29H/+." (PMID 40334547, 2025). "TXNRD1 inhibitor can cause immunogenic cell death (ICD) in vivo, encourage DC maturation, and elicit T-cell responses, all of which lead to tumor regression." (PMID 39744566, 2025). "We found that not only was TXNRD1 essential for Nrf2D29H-mediated tumor progression, but TXNRD1 KO tumors also exhibited an increase in macrophage infiltration." (PMID 40334547, 2025). "Like what we observed in the GSR KO model, we found that TXNRD1/GSR DKO significantly reduced tumor number (tumor initiation) in both the KrasG12D/+, Nrf2+/+ mice and KrasG12D/+, Nrf2D29H/+ models." (PMID 40334547, 2025). "Short interfering RNAs (siRNAs) studies targeting TXNRD1 further highlight its critical role in tumor progression." (PMID 41300507, 2025). "In breast cancer, high TXNRD1 expression correlates with poor prognosis and increased metastatic potential, underscoring its role in tumor progression." (PMID 41333220, 2025).
tumor (continued). "The result of model with 10 genes showed that 6 genes of MYCN, NDRG1, TXNRD1, SNAPC2, PHOSPHO2 and CDCA8 were more significantly associated with diagnosis of tumor according to the statistical filter of P < 0.05." (PMID 40465781, 2025). "In summary, thus far the data only show a causative link between TXNRD1 inhibitor treatment and increased B16F10 tumor burden." (PMID 41300507, 2025). "The mIHC images revealed that marker genes of epithelial cells (EPCAM, DSP and TXNRD1) were highly expressed in tumor regions, especially in the metastasis-related regions." (PMID 39741182, 2025). "This was accompanied by a decrease in grade 2 tumor size in the Nrf2+/+ TXNRD1/GSR DKO mice compared to Nrf2+/+ TXNRD1/GSR WT mice." (PMID 40334547, 2025). "This upregulation facilitated tumor cell ferroptosis by suppressing the novel target TXNRD1 and promoting lipid peroxidation within the tumor (p < 0.05)." (PMID 38462628, 2024). "The results obtained in this study would be useful in finding novel inhibitors of TXNRD1 and provide new insights into the anti-tumor activity of benzophenanthridine alkaloids." (PMID 37836684, 2023). "In the paired tumour sample analysis, the expression level of TXNRD1 in the tumour sample was the same as that in the normal sample." (PMID 37202783, 2023). "Our results demonstrated the TXNRD1 was significantly upregulated in HCC tumor tissues, which was also verified by database analysis." (PMID 36319631, 2022). "To validate these findings, we further examined the effects of TXNRD1 expression on in vivo tumor growth and metastasis of HCC cells in vivo." (PMID 36319631, 2022). "The TXNRD1 protein is involved in protecting cells from reactive oxygen species and also promotes tumor growth and DNA replication." (PMID 35277542, 2022). "The discovery of TXNRD inhibitors attracted considerable interest, due to the vital roles of TXNRD1 in tumor progression and metastasis." (PMID 36615301, 2022). "Here, we identified TXNRD1 as a tumor promoter that stimulates HCC proliferation and metastasis through activating AKT/mTOR signaling, and Upstream transcription factor 2 (USF2) was a major transcriptional repressor of TXNRD1 expression." (PMID 36319631, 2022). "In this study, we demonstrated that TXNRD1 was significantly upregulated in HCC tumor tissues and correlated with poor survival in HCC patients." (PMID 36319631, 2022). "Overexpression of TXNRD1 was detected in 62.5% (70/112) HCC tissues as compared with the adjacent non-tumor tissues." (PMID 36319631, 2022). "The results showed that knockdown of TXNRD1 in Bel-7402 cells significantly decreased the incidence of orthotopic liver tumor and the tumor volume compared to controls." (PMID 36319631, 2022). "Of note, the mRNA level of TXNRD1 in tumor displayed prominent downregulation 24 hours after systemic delivery miR-21–3p-AuNp, and was at forwardly reduced 48 hours after treatment." (PMID 35738798, 2022). "The protein expression level of TXNRD1 was significantly higher in HCC tumor tissues compared with their adjacent normal tissues." (PMID 36319631, 2022). "Consistently, TXNRD1 expression was significantly higher in tumor tissues compared with their adjacent normal tissues." (PMID 36319631, 2022). "In the present study, our data demonstrate that ATF3-induced miR-21–3 p upregulation contributed to the efficacy of anti-PD-1 immunotherapy by facilitating tumor cell ferroptosis via the suppression of the novel target TXNRD1 and lipid peroxidation." (PMID 35738798, 2022).
tumor (continued). "The use of TXNRD1 inhibitors auranofin can overload tumor cells with ROS and promote tumor cell death." (PMID 35646965, 2022). "The selenoprotein thioredoxin reductase 1 (TXNRD1) plays a vital role in protecting tumor cells against oxidative stress." (PMID 34485285, 2021). "According to their study, SLC27A5 deficiency promotes tumor proliferation and chemoresistance by increasing 4-HNE level and consequently activating KEAP1/NRF2/TXNRD1 pathway." (PMID 33731144, 2021). "MiR-328-3p acts as a tumor suppressor in HCC by inhibiting thioredoxin reductase 1 (TXNRD1), suggesting that it is a potential target for the clinical treatment of HCC." (PMID 34290743, 2021). "TXNRD1 was found to be overexpressed in HCC and associated with poor survival and advanced tumor staging." (PMID 34977159, 2021). "Multiplex antibody staining of NRF2 and thioredoxin reductase 1 (TrxR1) was conducted and scored in cytokeratin-positive (CK+) cells within the whole-tissue core as well as the tumor and stromal compartments of each tissue microarray (TMA) core." (PMID 34202448, 2021). "We can reasonably infer that the GPX3 gene mainly plays an inhibitory role in the process of tumor occurrence and development, while the TXNRD1 gene mainly plays a promoting role." (PMID 33706760, 2021). "The results revealed that the mRNA and protein level of TXNRD1 was dramatically upregulated in tumor tissues compared to adjacent healthy tissues." (PMID 33292234, 2020). "Our results indicated that miR-125b-5p represents a tumor suppressor in HCC through its attenuation of TXNRD1 levels, thereby suggesting this miRNA as a potential target for HCC treatment." (PMID 31384178, 2019). "Selenium is a strong antioxidant with proven anticancer properties, but several selenoproteins, such as thioredoxin reductase 1 and selenoprotein 15, have been shown to exhibit dual tumor-promoting and tumor-suppressive functions." (PMID 31737654, 2019). "Here, we demonstrated the tumor-suppressive property of miR-125b-5p via its targeting of TXNRD1, which broadens our understanding of the molecular mechanism associated with miR-125b-5p-related functions in HCC cells." (PMID 31384178, 2019). "Only positive correlations of gene expression with the Se level were observed for the SELENOF, SELENOK, and TXNRD1 genes, all in the tumor tissue (p = 0.001, 0.004, and 0.04, respectively), except for the normal tissue expression of SELENOK as well (p = 0.03)." (PMID 30469315, 2018). "Addition of the thioredoxin reductase 1 inhibitor (TXNRD1) auranofin (AF) to NSCLC cells treated with combination of TUSC2 forced expression with erlotinib increased tumor cell apoptosis and inhibited colony formation." (PMID 27845352, 2016). "We then examined the role of TXNRD1 on tumor progression by analyzing tumor grades." (PMID 40334547, 2025). "Using the Txnrd1flox allele to conditionally delete Txnrd1 only in lung cells exposed to cre recombinase, we generated KrasG12D/+; Nrf2+/+; Txnrd1Δ/Δ (TXNRD1 KO) and KrasG12D/+; Nrf2D29H/+; Txnrd1Δ/Δ (TXNRD1 KO) lung tumors to evaluate the requirement of TXNRD1 for tumor initiation and progression." (PMID 40334547, 2025). "Both auranofin and the more specific TXNRD1 inhibitor, TRi-1, suppress tumor development in PyMT-MMTV mice that spontaneously develop malignant breast tumors, as well as in other triple negative breast cancer models, particularly if combined with anti-PD-L1 antibody." (PMID 41300507, 2025). "Unlike what was observed upon GSR loss, we found that deleting TXNRD1 had no impact on tumor number (tumor initiation) in the KrasG12D/+, Nrf2+/+ or KrasG12D/+, Nrf2D29H/+ mice." (PMID 40334547, 2025). "We next examined the effect of TXNRD1/GSR DKO on tumor progression by analyzing tumor grades." (PMID 40334547, 2025).
tumor (continued). "We identified 9 genes whose increased expression was significantly associated with tumor size in female LC patients of which four code for MAPK signaling molecules (DUSP4, FGL1, TXNRD1, PLA2G4E), three for oncogenes (KRT16, STRIP2 and TNS4), tumor suppressor cystatin 5, and NQO1." (PMID 38245882, 2024). "Other tumour cell lines, such as A549, FaDu and HeLa cells, also express high levels of TXNRD1." (PMID 39110703, 2024). "Targeting TXNRD1 triggers ferroptosis and enhances the tumor-suppressive effect of ICIs." (PMID 38288118, 2023). "However, previous studies have shown that the downregulation of TXNRD1 can promote the production of reactive oxygen species, thereby promoting ferroptosis in tumor cells." (PMID 37834393, 2023). "In addition, the protein level of TXNRD1 in tumor was also remarkably downregulated 48 hours after treatment." (PMID 35738798, 2022). "USF2 functioned as tumor suppressor through the downstream repression of TXNRD1." (PMID 36319631, 2022). "Multiplex antibody staining of nuclear factor erythroid 2-related factor 2 (NRF2) and thioredoxin reductase 1 (TrxR1) was conducted and scored in cytokeratin-positive (CK+) cells within the whole-tissue core as well as the tumor and stromal compartments of each tissue microarray (TMA) core." (PMID 34202448, 2021). "The TXN components, for example TXN and TXNRD1, are reported to promote tumor growth." (PMID 33477494, 2021). "Oxidized Nm23-H1 lost its enzymatic activity and its ability to suppress tumor metastasis, specifically interacts with thioredoxin reductase 1 (TrxR1), which is known as a selenium-containing pyridine nucleotide disulfide oxidoreductase catalyzing NADPH-dependent reduction of Trx29." (PMID 33753879, 2021). "Moreover, with the success of using miRNA-conditioned media as an ROS inducer in our previous assays, we tested to see if cell-free conditioned media from miR526b/miR655-high cells regulate TXNRD1 expression in both tumor and endothelial cells." (PMID 31430859, 2019). "Furthermore, western-blot analysis was used to analyze the expression levels of PCK1 and TXNRD1 in the xenograft tumor tissues." (PMID 30619751, 2018). "The inverse association of TXNRD1 and TXNIP with MFI found in this study supports the hypothesis that the maintenance of an active thioredoxin system is advantageous to the tumor cells because it limits oxidative damage and enables them to survive." (PMID 20584310, 2010). "The thioredoxin redox system has been suggested recently as a therapeutic target for cancer therapy, based on the observation that thioredoxin is overexpressed in many aggressive tumors and that siRNA-mediated knockdown of TXNRD1 decreased tumor progression and metastasis in mice." (PMID 20584310, 2010). "Similarly, TXNRD1 is also highly expressed in diverse malignancies and promotes tumor progression." (PMID 34595103, 2021). "Using TCGA datasets, we then explore the mRNA levels of TXN, TXNRD1, and TXNIP in tumor and adjacent normal tissues and found similar results." (PMID 39744566, 2025). "To further investigate the relationship between Trx system and tumor immunity, we obtained the mRNA expression level of TXN, TXNRD1 and TXNIP at single-cell level using 10 datasets from TISCH data." (PMID 39744566, 2025). "The high expression of TXN and TXNRD1, as well as the low expression of TXNIP group exhibited lower levels of tumor immune infiltration." (PMID 39744566, 2025). "Using mice with conditional expression of neutrophil cytosolic factor 1 (NCF1), we found that both TXNRD1 inhibition and APC-specific NCF1-NOX2-ROS expression enhanced tumor burden and Treg expansion." (PMID 41300507, 2025). "Surprisingly, there was a significant increase in the burden of Nrf2+/+ alveolar hyperplasia (AAH) and grade 1 tumors upon TXNRD1 KO, which was accompanied by an increase in AAH and grade 1 tumor size." (PMID 40334547, 2025).
tumor (continued). "Using the CPTAC database, we verified that TXN, TXNRD1 and TXNIP proteins were also aberrantly expressed in the tumor." (PMID 39744566, 2025). "We evaluated the stromal and immune cells in tumor tissues using the ESTIMATE method, and found that stromal and immune scores were lower in the high TXN, high TXNRD1, and low TXNIP groups in most tumor species." (PMID 39744566, 2025). "Alternatively, sorted T cells from mice harboring conditional TXNRD1 knockouts showed reduced FOXP3 and GITR expression in the naïve state and reduced tumor burden when challenged with B16F10." (PMID 41300507, 2025). "In this paper, TXN, TXNRD1 and TXNIP are integrated for the first time to comprehensively analyze the importance and indication of the Trx system in tumor and immunotherapy." (PMID 39744566, 2025). "In this study, we reanalyzed publicly available single-cell RNA sequence data of HCC tumors and identified a distinct tumor cell cluster characterized by reduced SELENOP expression, enhanced GPX4 and TXNRD1 expression, and activation of NRF2 signaling." (PMID 40818321, 2025). "The results showed that the expression levels of ADK, ADSL, ATIC, DPYS, ENTPD2, TXNRD1, and UCK2 in at least one tumor cell line were consistent with the predictions." (PMID 37999212, 2023). "Then, we evaluated TXNRD1 protein level in 112 paired HCC tumor and adjacent non-tumor tissues by western blot." (PMID 36319631, 2022). "The result showed that the protein levels of TXNRD1 and phospho-Akt were consistently higher in HCC tumor tissues compared with their adjacent normal tissues, while a consistently opposite expression pattern of USF2 was detected." (PMID 36319631, 2022). "Here, we assessed the mRNA and protein expression of thioredoxin reductase 1 (TrxR1), a master regulator of cellular redox homeostasis, in GBM and non-tumor brain tissues." (PMID 36555352, 2022). "Targeting TXNRD1 leads to a dramatic accumulation of ROS, which is deemed to be an effective way to suppress HCC tumor growth." (PMID 36249031, 2022). "We also determined the protein expression of TXNRD1, USF2, and phospho-Akt in paired HCC tumor tissues." (PMID 36319631, 2022). "Simultaneous deletion of GSR and TXNRD1 reduced initiation and progression independent of Nrf2 status, but surprisingly did not completely abrogate tumor formation." (PMID 40334547, 2025). "We focused on TXNRD1 and GSR, the key mediators of the thioredoxin- and glutathione-dependent systems, and deleted these enzymes alone or in combination to study their roles in tumor initiation and early progression." (PMID 40334547, 2025). "A major advantage of our study over initial treatment studies is that we leverage these findings by using the B16F10 in C57BL6 mice to demonstrate TXNRD1 inhibitors are sufficient in augmenting Treg frequencies and tumor burden without other interventions." (PMID 41300507, 2025). "In contrast, Nrf2D29H tumors, but not Nrf2WT, were dependent on TXNRD1 for tumor progression, while GSR was dispensable." (PMID 40334547, 2025). "We do not demonstrate a continuous causal chain to show TXNRD1 inhibitors elevate APC ROS levels that in turn drive Treg expansion and immune suppression, leading to augmented tumor growth." (PMID 41300507, 2025). "Furthermore, the nude mice injected with shUSF2-transfected HLF cells were found have larger tumor volume and tumor weight than those injected with control cells, while this enhancement by knockdown of USF2 was blocked by knockdown of TXNRD1." (PMID 36319631, 2022). "TXNRD1 works as an oncogene in HCC and an TXNRD1 inhibitor significantly inhibits tumor growth." (PMID 33869278, 2021). "The GPX3 and TXNRD1 genes had the strongest negative and positive correlation with the tumor stemness, respectively." (PMID 33706760, 2021).